WFS1 (wolframin ER transmembrane glycoprotein)
Description:
Participates in the regulation of cellular Ca(2+) homeostasis, at least partly, by modulating the filling state of the endoplasmic reticulum Ca(2+) store. Negatively regulates the ER stress response and positively regulates the stability of V-ATPase subunits ATP6V1A and ATP1B1 by preventing their degradation through an unknown proteasome-independent mechanism.
Synonyms: DIDMOAD; WFS; CTRCT41; WFRS; WFSL; formerly DFNA6; DFNA14; DFNA38
Tractability: Antibody: UniProt predicts a signal peptide or a membrane-spanning region. PROTAC: ubiquitination databases record sites on it; its protein half-life has been measured.
Gene: Protein-coding gene on chromosome 4 (6,269,839 to 6,303,265, forward strand). Ensembl gene ENSG00000109501.
Subcellular location: Endoplasmic reticulum membrane; Cytoplasmic vesicle, secretory vesicle
Pathways (Reactome):
Metabolism of proteins: Post-translational protein phosphorylation; Regulation of Insulin-like Growth Factor (IGF) transport and uptake by Insulin-like Growth Factor Binding Proteins (IGFBPs)
Cellular responses to stimuli: XBP1(S) activates chaperone genes
Gene Ontology:
Molecular function: ATPase binding; protein binding; protein carrier chaperone; ubiquitin protein ligase binding; calcium-dependent protein binding; calmodulin binding; DNA-binding transcription factor binding; proteasome binding
Biological process: calcium ion homeostasis; endoplasmic reticulum calcium ion homeostasis; ER overload response; ERAD pathway; glucose homeostasis; kidney development; negative regulation of apoptotic process; negative regulation of ATF6-mediated unfolded protein response; negative regulation of neuron apoptotic process; negative regulation of programmed cell death; negative regulation of response to endoplasmic reticulum stress; negative regulation of transcription by RNA polymerase II; negative regulation of type B pancreatic cell apoptotic process; nervous system process; positive regulation of calcium ion transport; positive regulation of protein metabolic process; positive regulation of protein ubiquitination; protein stabilization; renal water homeostasis; response to endoplasmic reticulum stress; sensory perception of sound; visual perception; endoplasmic reticulum unfolded protein response; positive regulation of growth; intracellular signal transduction; and 4 more
Cellular component: endoplasmic reticulum; endoplasmic reticulum membrane; secretory granule; dendrite; endoplasmic reticulum lumen; synaptic vesicle membrane; transport vesicle
Genetic constraint (gnomAD): Loss-of-function variants: 90 observed, 65.39 expected, observed/expected ratio (o/e) 1.38, 90% interval 1.16 to 1.64. The synonymous counts are far from expectation, so gnomAD's model fits this gene poorly and the ratio says little. Missense variants: 1,767 observed, 1,220.8 expected, observed/expected ratio (o/e) 1.45, 90% interval 1.39 to 1.5. Synonymous variants: 860 observed, 540.86 expected, observed/expected ratio (o/e) 1.59, 90% interval 1.5 to 1.68.
Gene-disease validity (ClinGen):
ClinGen rates the evidence that WFS1 causes each of these diseases.
nonsyndromic genetic hearing loss (autosomal dominant): Definitive. A disease characterized by hearing loss that is not part of a larger syndrome.
Wolfram syndrome (autosomal recessive): Definitive. Wolfram syndrome (WS) also known as DIDMOAD, is a neurodegenerative disorder characterized by type I diabetes mellitus (DM), diabetes insipidus (DI), sensorineural deafness (D), bilateral optical atrophy (OA) and neurological signs.
Wolfram-like syndrome (autosomal dominant): Definitive. Wolfram-like syndrome is a rare endocrine disease characterized by the triad of adult-onset diabetes mellitus, progressive hearing loss (usually presenting in the first decade of life and principally of low to moderate frequencies), and/or juvenile-onset optic atrophy.
Homologues: Orthologues: chimpanzee WFS1 (99% identical), macaque WFS1 (98% identical), mouse Wfs1 (87% identical), rat Wfs1 (86% identical), guinea pig WFS1 (86% identical), pig WFS1 (85% identical), dog WFS1 (84% identical), tropical clawed frog wfs1 (73% identical), zebrafish wfs1b (55% identical), zebrafish wfs1a (48% identical), Drosophila melanogaster wfs1 (22% identical).
Diseases named in the same sentence as WFS1 in open-access papers:
WFS1 is named in the same sentence as 154 diseases in open-access papers, as found by Europe PMC text mining. Sharing a sentence is not in itself a finding about the gene and the disease. The quoted sentences say what the papers report.
Wolfram syndrome (198 papers, 2007 to 2026). "BACKGROUND: Wolfram syndrome is a rare disease caused by the mutation of WFS1 gene, characterized as s spectrum of disorders." (PMID 41896889, 2026). "Wolfram syndrome is a neurodegenerative disorder caused by ER dysfunction due to pathogenic WFS1 variants." (PMID 41323015, 2025). "For example, chemotherapy resistance and metabolic diseases like Wolfram syndrome brought on by WFS1 mutations are caused by disruption of apoptosis and autophagy balance." (PMID 41399527, 2025). "Hearing impairment, which affected nearly 15% of the reported families, was mainly observed in Wolfram syndrome and autosomal dominant hearing impairment caused by WFS1 variants, followed by variants of POLG, OPA1, DNMT1 and SLC25A46." (PMID 39423307, 2025). "Wolfram syndrome is a neuropsychiatric disorder caused due to WFS1 deficiency in astrocytes, this causes delayed neuronal differentiation, disrupted synapse formation, hampers neurite growth." (PMID 40255860, 2025). "This is also well substantiated in the case of Wolfram syndrome, where diabetes is a core element of its phenotype, caused by mutations in the WFS1 or CISD2 genes." (PMID 41234236, 2025). "WFS1 is linked to Wolfram Syndrome 1 (WS1), a severe neurodegenerative disorder that includes short stature as one of its clinical manifestations." (PMID 40607659, 2025). "Splicing mutations in WFS1 lead to aberrant transcripts that increase β‐cell apoptosis under stress in Wolfram syndrome." (PMID 41399527, 2025). "Mutations in the WFS1 gene are implicated in Wolfram syndrome (WS), Wolfram‐like syndrome (WFLS), and maturity‐onset diabetes of the young (MODY)." (PMID 40641032, 2025). "Wolfram syndrome (WS) is an autosomal recessive neurodegenerative disorder caused by pathogenic variants in the WFS1 gene." (PMID 39944315, 2025). "In Wolfram syndrome, mutations in WFS1 or CISD2 disrupt ER Ca2+ handling, impairing IP3R-mediated Ca2+ transfer to mitochondria." (PMID 41415579, 2025). "Loss of function mutations in the WFS1 gene cause Wolfram syndrome, which is characterized by juvenile‐onset diabetes mellitus, diabetes insipidus, neurodegeneration, hearing loss and optic nerve atrophy." (PMID 40955171, 2025). "In monogenic disorders like Wolfram syndrome, mutations in WFS1 cause unresolved ER stress and direct β-cell damage." (PMID 41323015, 2025). "Their strong correlations with ataxia indicate that cerebellar dysfunction in Wolfram syndrome is closely linked to the severity and structural configuration of WFS1 variants." (PMID 41464213, 2025). "Repairing a pathogenic splice‐site mutation in the WFS1 gene prevents β‐cell apoptosis and restores the normal transcriptome in wolfram syndrome." (PMID 41399527, 2025). "In Wolfram syndrome, pancreatic β-cells and neuronal cells undergo selective degeneration due to mutations in the WFS1 gene." (PMID 41306145, 2025). "While early research linked mutations in the WFS1 gene to rare Wolfram syndrome, recent studies have revealed a broader role for WFS1, potentially impacting the prognosis of lung cancer, rectal cancer, and colon cancer through its expression levels." (PMID 39478865, 2024). "Variants of the WFS1 gene are responsible for both Wolfram syndrome and autosomal dominant non-syndromic hearing loss (DFNA6/14/38)." (PMID 39200993, 2024). "Pancreatic β-cell failure by WFS1 deficiency is manifested in individuals with wolfram syndrome (WS)." (PMID 38321214, 2024). "As for gene editing, CRISPR technology is employed to target and correct the WFS1 gene mutation with wild-type alleles in Wolfram syndrome." (PMID 39064493, 2024). "Wolfram syndrome is an autosomal recessive disorder caused by endoplasmic reticulum dysfunction due to mutations in the WFS1 or WFS2 genes, whereas both DOA and LHON are associated with mitochondrial dysfunction." (PMID 39835089, 2024). "WFS1 has primarily been associated with Wolfram syndrome, a genetic disorder characterized by optic atrophy and peripheral neuropathy." (PMID 39015129, 2024).
Wolfram syndrome (continued). "The c.2051C>T variant was also found in patients with coexisting hearing impairment and optic atrophy with heterozygous variant in the WFS1 gene and in a patient with Wolfram syndrome as one of two missense mutations." (PMID 39766859, 2024). "Genetic testing identified two heterozygous variants in the WFS1 gene (c.1672C>T and c.1234_1237delGTCT), and she was diagnosed with Wolfram syndrome." (PMID 39766859, 2024). "Four patients in the study group were diagnosed with Wolfram syndrome and all were compound heterozygotes for variants in the WFS1 gene." (PMID 39766859, 2024). "WFS1-spectrum disorder (WFS1-SD) is caused by a mutation in the WFS1 gene, ranging from the phenotypically most severe Wolfram syndrome to diseases with a milder clinical course." (PMID 39766859, 2024). "The study provided insight into the impact of specific variants on patients with both Wolfram syndrome and milder disorders in the form of WFS1-SD." (PMID 39766859, 2024). "The WFS1 gene is known to cause Wolfram syndrome, a neurodegenerative disease characterized by diabetes insipidus, diabetes mellitus, optic atrophy, deafness, and other neurological and psychiatric problems." (PMID 37650104, 2023). "Dominant WFS1 variants potentiate ER stress and result in pathophysiology that is distinct and less severe than patients with recessive Wolfram syndrome." (PMID 37415600, 2023). "In contrast, recessively inherited variants in WFS1 are responsible for Wolfram syndrome type 1, also known as DIDMOAD syndrome (diabetes insipidus, diabetes mellitus, optic atrophy, and deafness)." (PMID 37041640, 2023). "To extend our findings to an in vivo humanised Wolfram syndrome model, we transplanted iPSC-derived beta cell aggregates from two WFS1-deficient individuals and an isogenic control under the kidney capsule of immunodeficient Rag2 KO mice." (PMID 36995380, 2023). "WS is mainly caused by mutations in WFS1 gene that are responsible for the classical form of Wolfram syndrome 1 (WS1)." (PMID 37752530, 2023). "Wolfram syndrome is a neurodegenerative disorder caused by pathogenic variants in the genes WFS1 or CISD2." (PMID 37508961, 2023). "Wolfram Syndrome (WS) is a rare condition caused by mutations in Wfs1, with a poor prognosis and no cure." (PMID 37900147, 2023). "Wolfram syndrome is a rare autosomal recessive disorder caused by pathogenic variants in the WFS1 gene." (PMID 36995380, 2023). "Pathogenic WFS1 variants cause a spectrum of different disorders, including Wolfram syndrome (OMIM 222300), Wolfram-like syndrome (OMIM 614296) and DFNA6/14/38 (OMIM 600965)." (PMID 36833385, 2023). "The Wolfram syndrome 1 gene (WFS1) is the main causative locus for Wolfram syndrome, an inherited condition characterized by childhood-onset diabetes mellitus, optic atrophy, and deafness." (PMID 37859980, 2023). "Wolfram syndrome 1 (WS1) is a rare genetic disorder caused by mutations in the WFS1 gene leading to a wide spectrum of clinical dysfunctions, among which blindness, diabetes, and neurological deficits are the most prominent." (PMID 36645345, 2023). "Wolfram syndrome 1 (WFS1) gene mutations can be dominantly or recessively inherited, and the onset of the clinical picture is highly heterogeneity in both appearance and degree of severity." (PMID 36816038, 2023). "Two siblings who were diagnosed with diabetes at 7 and 12 years of age and who had a short stature had a homozygous mutation in WFS1 causing Wolfram syndrome." (PMID 37897565, 2023). "Several studies have linked variations in the WFS1 gene to Wolfram Syndrome, an autosomal recessive disorder, and T2DM susceptibility." (PMID 36980809, 2023). "Although the link between Wfs1 and autism is still unproven, it has been demonstrated that a mutation in WFS1 causes Wolfram syndrome, which is associated with bipolar disorder and SCZ." (PMID 36830826, 2023).
Wolfram syndrome (continued). "Wolfram syndrome 1 (WS1) is a rare autosomal recessive neurodegenerative disease caused by mutations in WFS1 and WFS2 genes that produce wolframin, a protein involved in endoplasmic reticulum calcium homeostasis and cellular apoptosis." (PMID 36835101, 2023). "Diabetes is one of the most common phenotypes of Wolfram syndrome owing to the presence of the variants of the WFS1 gene and is often misdiagnosed as other types of diabetes." (PMID 37277527, 2023). "For example, variants in WFS1, a gene involved in both autosomal non-syndromic hearing loss and Wolfram syndrome, showed significant associations with cisplatin-induced ototoxicity in testicular cancer survivors." (PMID 37062025, 2023). "Six (0.9%) patients carried pathogenic or likely pathogenic variants; they met the diagnostic criteria for WFS1-DM according to the latest guidelines, but typical phenotypes of Wolfram syndrome were seldom observed." (PMID 37277527, 2023). "WFS1 mutation leads to the Wolfram syndrome, of which the most common clinical phenotypes are early onset diabetes and neurological symptoms." (PMID 37540242, 2023). "Wolfram syndrome (WS) is a rare autosomal recessive disorder caused by mutations in the WFS1 or CISD2 genes, with a global prevalence of one in 500,000." (PMID 37974252, 2023). "For example, WFS1 (Wolframin ER transmembrane glycoprotein) mutations, which are found in 95% of Wolfram syndrome patients, lead to GLI1 degradation in in vitro analyses." (PMID 37476499, 2023). "Mutations in the WFS1 gene encoding the Wolframin1 protein (WFS1) cause the classical form of the rare condition Wolfram Syndrome (WS)." (PMID 37900147, 2023). "Loss of the MAM-resident protein WFS1 causes Wolfram syndrome (WS), a rare early-onset neurodegenerative disease that has been linked to mitochondrial abnormalities." (PMID 37163979, 2023). "In future studies, focusing on the effects of different types of mutants on the function of the WFS1 protein and will reveal the link between different mutation sites in the pathogenesis of Wolfram syndrome." (PMID 37974252, 2023). "Approach: Patient data from the Washington University International Registry and Clinical Study for Wolfram Syndrome and patient case reports were analyzed to select for patients with two recessive mutations in the WFS1 gene." (PMID 37415600, 2023). "Clinical investigation revealed that most patients carrying the homozygous WFS1 c.1672C>T, p.R558C variant developed diabetes mellitus; however, the age at diagnosis was greater than that of typical Wolfram syndrome (approximately 6 years)." (PMID 36134655, 2022). "This is consistent with the previous results obtained in iPSC-based model of Wolfram syndrome 1, with the patient’s cells carrying mutation in the WFS1 gene and showing incapability of forming pancreatic organoids during differentiation." (PMID 35955956, 2022). "Wolfram syndrome 1 caused by homozygous or compound heterozygous mutations in WFS1 (encoding wolframin, a 100-kDa transmembrane glycoprotein localized in the secretory granules and endoplasmic reticulum [ER])." (PMID 35227307, 2022). "Pathogenic variants in the WFS1 gene are generally associated with Wolfram syndrome (WS), Wolfram-like syndrome (WLS) and LFSNHL." (PMID 36225977, 2022). "Clinical investigation indicated that patients carrying the homozygous WFS1 c.1672C>T, p.R558C variant showed mild forms of Wolfram syndrome phenotypes." (PMID 36134655, 2022). "Wolfram syndrome is a rare disease caused by pathogenic variants in the WFS1 gene with progressive neurodegeneration." (PMID 35495027, 2022). "The WFS1 p.Arg558Cys missense variant is associated with mild syndromic manifestations of Wolfram syndrome." (PMID 36613674, 2022). "Wolfram syndrome is caused by pathogenic variants in the WFS1 gene, which encodes wolframin, a transmembrane ER glycoprotein involved in intracellular calcium homeostasis and regulation of unfolded protein response." (PMID 35495027, 2022).